ENSG00000286022 (novel protein)
Gene: Protein-coding gene on chromosome 20 (2,207,328 to 2,341,059, forward strand). Ensembl gene ENSG00000286022.
Genetic constraint (gnomAD): Loss-of-function variants: 51 observed, 72.24 expected, observed/expected ratio (o/e) 0.71, 90% interval 0.56 to 0.89. Missense variants: 915 observed, 931.28 expected, observed/expected ratio (o/e) 0.98, 90% interval 0.93 to 1.04. Synonymous variants: 369 observed, 368.09 expected, observed/expected ratio (o/e) 1, 90% interval 0.92 to 1.09.